CD28 (CD28 molecule)
Diseases named in the same sentence as CD28 in open-access papers (continued):
Sharing a sentence is not in itself a finding about the gene and the disease.
type 1 diabetes (25 papers, 2011 to 2025). "PRKCQ, encoding a member of the protein kinase C (PKC) family, is associated with type 1 diabetes by a large GWAS evidence, which could control biological processes involving T-cell integration and CD28 signaling." (PMID 41393296, 2025). "Polyclonal cells, obtained by anti-CD3 and anti-CD28 stimulation, exert positive effect on patients with type 1 diabetes and significantly reduce the inflammatory response." (PMID 33868279, 2021). "Whereas in our pathway analysis, more genes are identified as part of Type I diabetes mellitus and Allograft rejection pathways (i.e. CD28, HLA-B, HLA-C, HLA-DMB, HLA-DPA1, HLA-DQA2, HLA-DRA, IL12A)." (PMID 22046267, 2011). "Similarly, pre-existing CMV infection promoted the expansion of CD28− CD8+ T cells during the progression of Type 1 Diabetes (T1D)." (PMID 35328795, 2022). "Furthermore, consistent with immune dysregulation in type 1 diabetes, CD4+ Teff activated PD1high were decreased in type 1 diabetes patients at day 6 of anti-CD3/CD28 stimulation upon Pep3 pretreatment." (PMID 31995625, 2020). "Moreover, our data on the inhibitory effects of ISA-2011B on CD28-mediated upregulation of inflammatory cytokines related to Th17 cell phenotype in type 1 diabetes patients suggest ISA-2011B as a promising anti-inflammatory drug." (PMID 28491063, 2017). "Finally, the results obtained by analyzing the effects of ISA-2011B on CD28-mediated upregulation of inflammatory IL-8, IL-6, and IL-17A genes in T lymphocytes from type 1 diabetes (T1D) patients suggest ISA-2011B as a promising anti-inflammatory drug." (PMID 28491063, 2017). "Our analysis suggested that SESN3 may reduce T cell expression of CD3, a co-receptor essential for T cell activation and the target of teplizumab (a monoclonal antibody approved to delay the onset of stage 3 type 1 diabetes), and CD28, a key activator of T cells." (PMID 41299435, 2025). "In RA, type 1 diabetes (T1D), multiple sclerosis (MS), Graves’ disease (GD), and granulomatosis with polyangiitis, CD4+CD28- T cells are capable of infiltrating inflamed tissues and exacerbating immune-mediated damage." (PMID 40852730, 2025). "Healthy subjects had higher levels of galectin-10, CD24, CD197, CD196, CD25 and CD45RO and patients with type 1 diabetes had higher levels of CD16, CD45RA, CD274, HLA-DR, CD28, Interleukin (IL)-5R, and CD38." (PMID 37210405, 2023). "We have also looked at Tregs and Teffs unspecific to the antigens (index UNSPEC) as well as those expanded with anti-CD3/anti-CD28 beads used currently as the polyclonal (index POLY, 1:1 ratio bead:cell) in the treatment of type 1 diabetes." (PMID 33868279, 2021). "In order to investigate T cell activation following Pep3 treatment, in HD and type 1 diabetes PBMC, expression of the regulatory PD1 molecule was studied after 24 hrs treatment with the peptide and subsequent anti-CD3/CD28 stimulation." (PMID 31995625, 2020). "We have recently reported that CD28 autonomous signaling induces the expression of IL-17A in peripheral CD4+ T lymphocytes from healthy donors, multiple sclerosis, and type 1 diabetes patients." (PMID 31068940, 2019). "For this purpose, human CD3+ T cells were isolated from PBMCs of control subjects and patients with type 1 diabetes, activated using anti-CD3 and anti-CD28 and cultured as described in the Research Design and Methods section." (PMID 25279717, 2014). "In addition, human Tregs can be isolated from newly-onset type 1 diabetes patients and expanded in vitro with anti-CD3 and anti-CD28 in the presence of high doses of recombinant IL-2." (PMID 25279717, 2014).
HIV-1 infection (23 papers, 2004 to 2024). The type species of lentivirus and the etiologic agent of acquired immunodeficiency syndrome (AIDS). "Gradual loss of CD28 on T cells has been shown to be the result of aging as well as prolonged antigenic stimulation during HIV-1 infection; effective ART administration has however been shown to shift this pathological parameter into a state where the majority of CD8 + T cells express CD2830." (PMID 33235273, 2020). "Although naïve T cells show lower levels of CCR5 expression and higher levels of CXCR4 in comparison to memory cells, they were shown to possess a higher in vitro susceptibility to R5 HIV-1 infection than memory T cells following stimulation with immobilized anti-CD3 plus anti-CD28 Ab." (PMID 21284907, 2011). "HIV-1 infection characteristically induces T-cell activation markers, particularly upregulated expression of CD38 and HLA-DR, and loss of CD28 on circulating CD8 T cells." (PMID 39221258, 2024). "In the primary CD4+ T cells, phospho-p105 was detected in all conditions, including uninfected cells, due to NF-κB activation induced by the CD3/CD28 co-stimulation conducted prior to HIV-1 infection." (PMID 37341489, 2023). "Here, PMA induced 10-fold or 3-fold more reactivation than CD3/CD28 stimulation, indicating that the phenomenon of HIV-1 infection induced TCR/CD3 reactivation that we observed in primary T cells is effectively reproduced in T cell lines." (PMID 33465149, 2021). "In order to manipulate signal strength received by a T cell at the time of HIV-1 infection, we utilized chimeric antigen receptors (CARs) that recapitulate T cell receptor and CD28 signaling." (PMID 31116788, 2019). "Upon co-stimulation with CD3/CD28 antibodies, activated CD4 + T cells were found to lose their susceptibility to HIV-1 infection, exhibiting an induced resistant phenotype." (PMID 23635305, 2013). "Removal of anti-CD3 and CD28 after HIV-1 infection reduced the percentage of GFP+ T cells 5–10-fold to 0.5–1%." (PMID 18446227, 2008). "The original observation that magnetic-bead bound CD3 and CD28 antibodies prevent monocytotropic HIV-1 infection of peripheral blood CD4-positive T cells spawned two approaches that were experimentally tested." (PMID 17504532, 2007). "Increased proportions of CD28−/CD27+ CD8+ T-cells during acute HIV-1 infection are likely to reflect expansion of HIV-specific CD8+ T-cells." (PMID 14966528, 2004). "This phenomenon suggests that the permissive state for HIV-1 infection induced by IL-7 is associated with an increased responsiveness to activation via CD3 and CD28." (PMID 14737186, 2004). "We found that the stimulation of resting CD4+ T cells with either PHA-P or the anti-CD3/CD28 antibodies could significantly diminish SUN2 expression, which helps to explain the increased susceptibility of activated primary CD4+ T cells for HIV-1 infection." (PMID 29717016, 2018). "Alterations in activation status of infected cells, which may in part be achieved through CD28 downregulation, could have effects in vivo during HIV-1 infection." (PMID 29329537, 2018). "From our results, we did not see an increase in susceptibility to HIV-1 infection in the CD28+, CD38+ or HLA-DR+ CD8+ T-cell subsets." (PMID 18923697, 2008). "In addition, the naïve CD8+ T-cell population has also been shown to be the most susceptible to HIV-1 infection following activation-induced up-regulation of the CD4 cell-surface molecule by antibodies to CD3 and CD28." (PMID 18923697, 2008). "If the CD8+CD28- cells are indeed involved in the suppression of HIV-1 replication and, based upon our observations, show an increase in susceptibility to HIV-1 infection, then a key subset of CD8+ T-cells involved in fighting disease may be hampered or eliminated early on in the course of disease." (PMID 18923697, 2008).
HIV-1 infection (continued). "Here, we used polychromatic flow cytometry to examine the co-expression of CD38, CD27 and CD28 on total T cells and antigen-specific (HIV, CMV) T cells in a cohort of adults in early HIV-1 infection (within 6 months of acquisition)." (PMID 19198651, 2009). "Although chromosomal integration of HIV-1 proviral DNA was inefficient in mouse T cells pre-activated with anti-CD3 and anti-CD28, this block was substantially relieved by providing a secondary TCR signal after HIV-1 infection." (PMID 18446227, 2008). "This is consistent with previous studies showing that anti-CD28 down-regulates CCR5 in human T cells, inhibiting R5 tropic HIV-1 infection." (PMID 18446227, 2008). "Upon stimulation with CD3/CD28 beads the CTLA-4 expression levels were even significantly reduced in the elderly and the role of this inhibitory receptor for the pathogenesis of HIV-1 infection in vivo remains to be elucidated." (PMID 26452480, 2015). "To analyze the effect of the duration of HIV-1 infection and aging process on the T cell immune response, we assessed T cell differentiation and senescence (CD28+, CD57+, and CD57+CD28−) of both CD4+ and CD8+ T cells in two perinatally HIV-1 infected age groups on cART." (PMID 23029209, 2012). "Furthermore, sustained CD28 signaling, as well as IL-4, can upregulate the expression of CXCR4 and, consequently, favor X4 HIV-1 infection and replication in activated T cells." (PMID 21284907, 2011). "However, anti-CD3+CD28 treatment resulted in either no reactivation or a modest 1.8-fold reactivation in cells stimulated through the low affinity CAR at the time of HIV-1 infection." (PMID 31116788, 2019). "Treatment with anti-CD28 or IL-2 was neither necessary nor sufficient for enhanced HIV-1 infection." (PMID 18446227, 2008). "In contrast to HIV-1 infection in adults, we did not observe any age related alterations in CD57 or CD28 T cell expression." (PMID 23029209, 2012). "Indeed, HIV-1 infection of resting naïve CD4+ T cells results in an abortive non-replicative infection, whilst either mitogenic or anti-CD3/CD28 mediated stimulation of T cells drives production of replicating virus." (PMID 37006246, 2023).
psoriasis (21 papers, 2010 to 2025). An autoimmune condition characterized by red, well-delineated plaques with silvery scales that are usually on the extensor surfaces and scalp. "The production of TNF-α and IL-17 from CD3/CD28-stimulated T cells was also significantly increased, implicating these cytokines in the pathogenesis of psoriasis." (PMID 39998065, 2025). "Abatacept, a human CTLA-4 Ig that inhibits CD28 signaling, was previously shown to ameliorate human psoriasis." (PMID 38226171, 2024). "Conversely, two traits showed protective connections with psoriasis: CD28 on CD39+ activated Treg (IVW: OR 0.9995, 95% CI 0.9990–1.0000; p = 3.250596e−02), CD25 on CD39+ CD4 Treg (IVW: OR 0.9984, 95% CI 0.9973–0.9995; p = 3.969029e−03)." (PMID 38558803, 2024). "CD28 costimulation has been studied in the development and maintenance of psoriasis lesions, with disease improvement and decreased skin-infiltrating T cells observed in patients treated with CD28 blockers." (PMID 36675078, 2023). "The level of CTLA4, a traditional immune checkpoint molecule that inhibits T cell CD28(B7-1) costimulatory function, was reported to be negatively correlated with the severity of psoriasis." (PMID 34768720, 2021). "The role of co-signaling molecules in psoriasis is recognized, mainly including the co-stimulatory molecules CD28, CD40, OX40, CD27, DR3, LFA-1, and LFA-3 and the co-inhibitory molecules CTLA-4, PD-1, and TIM-3." (PMID 34354596, 2021). "Does blockade of CD28/B7 costimulatory signaling with abatacept suppress the psoriasis molecular signature and prevent psoriasis relapse after ustekinumab withdrawal?" (PMID 34643650, 2021). "Notable pathways included, “Role of IL-17A in Psoriasis”, “T Cell Receptor Signalling”, “CD28 Signalling in T helper Cells” and “IL-8 Signalling”." (PMID 32886659, 2020). "FK734, an Fc-silenced anti-CD28 mAb, demonstrated preclinical efficacy in a humanized model in which human psoriasis plaque from patients were grafted onto immunodeficient SCID mice." (PMID 31548534, 2017). "Among CD8+ cells, the terminally differentiated or senescent T cells (TEMRA as well as CD28- TEMRA) had higher proportions in psoriasis patients." (PMID 28790368, 2017). "Consistently, the role of CD28/CD80 in experimental models of psoriasis and in humans has been recently reviewed." (PMID 24676037, 2014). "Upon anti-CD3/anti-CD28 stimulation, psoriasis infiltrating T cells released more IL-17 (2.0 versus 1.5 ng/ml, p = 0.85) than ACD derived T cells." (PMID 25058585, 2014). "It was concluded that CD28/CD80 is crucial in promoting T cell inflammation in psoriasis and the effect of blocking CD28/CD80 signalling by CTLA-4 analogues or by anti-CD28 blocking antibodies is effective against PsA." (PMID 24676037, 2014). "Upregulation of CD80/CD86 in psoriatic lesions suggests a critical role for the CD28/B7 co-stimulatory system in the pathogenesis of psoriasis." (PMID 20606886, 2010). "It was observed that, after anti-CD3 and anti-CD28 stimulation, IL-10 levels were significantly lower in psoriasis patients treated with methotrexate and in patients on anti-TNF treatment than in healthy control subjects (p = 0.029 and p = 0.030, respectively)." (PMID 31101850, 2019). "Notably, our findings suggest that monitoring CD28 and CD127 expression levels on CD4+ TCM and CD4+ TN could be crucial in identifying psoriasis patients at high risk of developing arthritis." (PMID 38590608, 2024). "Upon anti-CD3/CD28 stimulation, CD8+CD45RA+CD45RO-CD27+ T cells (Cluster 15) were significantly increased in psoriasis compared to the healthy cohort." (PMID 40391222, 2025). "While CD28, TIGIT, BTLA and PD-1 are expressed by CD8 T cells, the costimulatory receptors LIGHT and CD134 are minimally expressed in both psoriasis patients and healthy controls (<2%)." (PMID 40391222, 2025). "In this investigation, we found that CD28 on CD39+-activated Treg and CD25 on CD39+ CD4 Treg were protective against psoriasis." (PMID 38558803, 2024).
psoriasis (continued). "The frequency of CD69+, Granzyme B+ and IFNγ+ CD8 T cells in psoriasis patients was significantly lower following anti-CD3/CD28 stimulation (p<0.0005), suggesting downregulated TCR-dependent activation and impaired Tc1 cytokine production in CD8 T cells from psoriasis patients." (PMID 40391222, 2025). "Total memory, central memory, effector memory, and naïve CD8 T cell subpopulations from psoriasis patients exhibited a significantly lower percentage of CD69+, Granzyme B+, and IFNγ+ cells compared to healthy controls when stimulated with anti-CD3/CD28." (PMID 40391222, 2025). "Our study reveals that CD28− CD127− CD25++ CD8br%CD8br, CD127− CD8br AC, and CD127 on CD8br may all enhance the chance of getting psoriasis." (PMID 38558803, 2024). "On the contrary, it was observed that, after stimulation with anti-CD3 and anti-CD28, there was a significant increase in CD4+ T cells of a regulatory phenotype (CD25hiFoxP3+LAP+) in untreated psoriasis patients compared with the group treated with methotrexate (p = 0.03)." (PMID 31101850, 2019). "Because both keratinocyte and immune cell activation are involved in the initiation and chronicity of psoriasis and other inflammatory skin diseases, we next examined the effect of fisetin on anti-CD3/anti-CD28-activated PBMC secretion of inflammatory mediators." (PMID 31540162, 2019). "Thus, inhibition of the CD28 and CD80/CD86 interaction is expected to restrict the inflammatory processes of psoriasis." (PMID 20606886, 2010). "Moreover, psoriasis patients demonstrate reduced expression of CD27 and CD28 on skin T cells." (PMID 38596682, 2024).
colitis (20 papers, 2009 to 2026). Inflammation of the colon. "CD8+CD28− T cells derived from IL-10–deficient mice lack the functional ability to prevent colitis." (PMID 19779562, 2009). "After this experiment, primed cADSCs were co-cultured for 3 days with CD4+ T-helper (Th) cells derived from the spleen of colitis mice stimulated with anti-CD3/CD28-coated beads, followed by flow cytometry measurement of Th cell proliferation." (PMID 39176394, 2024). "Administration of TA to mice with experimentally induced colitis strikingly suppressed weight loss, colon shrinkage, and IL-17 secretion from mesenteric lymph node lymphocytes in response to CD3/CD28 stimulation." (PMID 34589853, 2020). "In an IBD model, in contrast to CD8+CD28+, CD8+CD28− T cells freshly isolated from the spleen or gut of naïve mice, being rather “natural” Ts, effectively prevent the development of colitis." (PMID 19779562, 2009). "For instance, both intraepithelial CD28- CD8+ and lamina propria CD28- CD8+ equally prevented development of colitis in the CD4+ CD45RBhigh-induced colitis mouse model indicating that their location might be reflecting their demand not their function." (PMID 34707610, 2021). "In a murine model, naturally occurring CD8+CD28- Tregs and in vitro activated CD8+CD122+ T cells prevented CD4+CD45RBhi T cell-induced colitis." (PMID 39085655, 2024). "In a rat model of trinitrobenzenesulfonic acid-induced colitis, treatment with mesalazine, a therapy for ulcerative colitis (UC), increased the ratio of CD8+CD28+/CD8+CD28− T cells in the blood." (PMID 34831195, 2021). "Lymphocytes from the MLN of mice at 7 days after colitis induction were collected and stimulated with anti-CD3/CD28 antibodies to activate CD4+ T cells." (PMID 34589853, 2020). "Like the CD8/CD28− T cells, the mouse homologs of the human CD8/CXCR3+ T cells (CD8/CD122+) suppressed the development of T cell-transfer colitis via the production of IL-10." (PMID 24502291, 2014). "In CD4+CD25–CD45RBhi cell-induced colitis in Rag−/− mice, adoptive transfer of Cd28-ΔTreg cells resulted in more severe colitis compared to mice receiving WT Treg cells, revealing that Cd28-ΔTreg cells failed to suppress colitis." (PMID 34011962, 2021). "Severe colitis in HSD-fed mice was accompanied by a massive increase in neutrophils in colon tissue, increased anti-CD3/anti-CD28-stimulated production of IL-17 in mesenteric lymph nodes, and increased Tnfa expression and IL-6 and IL-1β production in the colonic tissue." (PMID 33339337, 2020). "Increased colitis in Rag KO recipients of VDR KO CD8+ T cells is not a result of a difference in the CD28+/− subpopulations." (PMID 24502291, 2014). "Their tolerogenic activity was observed in the model of experimental colitis, inflammatory bowel disease and in experimental autoimmune encephalitis (EAE), suggesting that targeting CD8+CD28- Tregs or their depletion may represent a potential strategy to enhance antitumor immunity in cancer." (PMID 36934257, 2023). "It was hypothesized that a D2R antagonist would inhibit the therapeutic effect of TA on DSS-induced colitis and might even exacerbate the colitis due to its ability to reverse TA-mediated modulation of cytokine secretion by LPS- and CD3/CD28-stimulated splenocytes." (PMID 34589853, 2020). "In the present study, the level of MHC-II was increased in DCs from the colitis mice without treatment along with over-expression of costimulatory molecules of DCs, including CD83, CD28, B7-DC, CD40, CD40 L, and TLR2." (PMID 27932984, 2016).